MUC1 (mucin 1, cell surface associated)
Diseases named in the same sentence as MUC1 in open-access papers (continued):
Sharing a sentence is not in itself a finding about the gene and the disease.
cancer (continued). "In addition, cancer-specific markers such as annexin-II and mucins such as MUC1 can be used as combination markers to detect LC cells in the circulation." (PMID 36980526, 2023). "The potential utility of various MUC1-based vaccine strategies has shown promise in eliciting immune responses in preclinical trials, leading to clinical trials in several cancers, including PDA, that have demonstrated a range of effects on humoral and T cell responses and patient survival." (PMID 35522218, 2022). "Although some secretory proteins in mucin family like Mucin 5AC have been proved to promote cancer invasion and development through driving stemness in exosomes or vesicle pathway, it is obvious that the secretory transformation of membrane-bound MUC1 was favorable to drug response." (PMID 35970845, 2022). "Similarly, inhibition of mitophagy significantly suppresses MUC1-induced cancer cell activity in vitro and in vivo." (PMID 36289190, 2022). "It has been shown that the tandem repeats of MUC1 play pivotal role in expression of pro‐inflammatory cytokines through activation of NF‐κB pathway and thereby inducing inflammation and progression of cancer." (PMID 34694686, 2022). "Altogether, these results illustrate that MUC1 promotes mitophagy in cancer cells." (PMID 36289190, 2022). "CAR T cell setting has been used for targeting MUC1 in cancer, too." (PMID 35248049, 2022). "There are many therapeutic drugs targeting MUC1 and PD-L1, such as MUC1-based cancer vaccines including mRNA vaccine, DNA vaccine, viral vaccine, DC vaccine and glycopeptide vaccine, and there are many anti-PD-L1 monoclonal antibodies, such as Atezolizumab, Avelumab and Duravulumab." (PMID 35891256, 2022). "Aptamers are under investigation for cancer therapy, and MUC1 aptamer could recognize MUC1-expressing TNBC cells well." (PMID 35248049, 2022). "Expressed nanobody demonstrated specificity only toward MUC1‐overexpressing cancer cells and could internalize in cancer cell lines." (PMID 34694686, 2022). "Most importantly, aberrant glycosylation of MUC1 triggers its endocytosis and accumulation in intracellular compartment, which has been proposed to change its function in intracellular signaling pathways in cancer cells." (PMID 34694686, 2022). "Besides, MUC1 increases cancer cells' binding to endothelial cells through the expression of E-selection." (PMID 35248049, 2022). "MUC-1 involves in apoptotic response in cancer cells and HBC, playing as a carcinogen in it." (PMID 35000604, 2022). "In addition, accumulating evidence shows that the oncoprotein MUC1 is regulated by various ncRNAs in the modulation of cancer development." (PMID 35154471, 2022). "In preceding research, they were functionalized by MUC-1 to target cancers that overexpress MUC-1." (PMID 35384774, 2022). "In cancer cells, MUC1 blocks cytochrome C, caspase 3 activity, and TRAIL-dependent apoptosis." (PMID 35248049, 2022). "As reported, applying MUC1 DNA vaccination only cannot sufficiently overcome cancer challenges." (PMID 35883508, 2022). "HzMUC1-ADC should also be an effective drug for the treatment of different MUC1-positive cancers." (PMID 36572921, 2022). "GO201 blocks MUC1 functions such as keeping the reactive oxygen species balance in cancer cells." (PMID 35248049, 2022). "Here, for the first time, we reveal that MUC1 augments mitophagy and triggers cancer development." (PMID 36289190, 2022). "The high expression of miRNA-1226 may induce cell death by inhibiting the expression of MUC1 oncoprotein, disrupt the surrounding microenvironment of cancer cells, and inhibit the metastasis of cancer cells." (PMID 34980146, 2022). "For instance, encouraging pre-clinical studies were presented concerning CAR-Ts targeting Tn and STn antigens in MUC1 97, which may now be adapted for more cancer specific proteoforms such as CD44-Tn/STn." (PMID 35547758, 2022).
cancer (continued). "Interestingly, MUC1 is overexpressed but underglycosylated in many cancer types and is believed to activate multiple signaling pathways in cancer cells." (PMID 35654773, 2022). "IC50 values of anti‐MUC1 tandem repeats nanobody for different cancer cell lines." (PMID 34694686, 2022). "Finally, we will also outline the results of the clinical trial exploiting glycosylated-MUC1 as a vaccine in different cancers." (PMID 36612133, 2022). "Likewise, in cancer, a self-adjuvanting multicomponent vaccine combining per-glycosylated MUC1 peptide and TLR2 agonist Pam3CysSer shows strong antibody generation in animal models." (PMID 36364057, 2022). "Because of overexpression and hypoglycosylation in cancer environment MUC1 has lost its polarity." (PMID 35351156, 2022). "In addition, MUC1 can be used as a target for monoclonal antibodies, antibody–drug conjugate, cancer vaccine, Aptamer, and radiotherapy." (PMID 35879749, 2022). "However, our data indicate that the combination of mitophagy inhibitors and chemotherapeutic drugs represents an encouraging method to overcome chemoresistance in several MUC1-expressing cancer types." (PMID 36289190, 2022). "These may explain in part why targeting MUC1 signaling pathways with anti‐MUC1 nanobody may significantly suppress cancer proliferation, migration, and metastasis." (PMID 34694686, 2022). "Such is the case of STn- and Tn-decorated MUC1, which is overexpressed in several malignant tumors." (PMID 35205658, 2022). "We mention why targeting MUC1 can be useful in overcoming trastuzumab resistance in cancer therapy." (PMID 35248049, 2022). "MUC1 enhances cancer stemness through the activation of pluripotency networks." (PMID 36289190, 2022). "The aberrant glycosylation and overexpression of MUC1 gene in cancer cells may lead to cancer invasion, metastasis, angiogenesis, and apoptosis by virtue of its participation in intracellular signaling processes and the regulation of related biomolecules." (PMID 35664298, 2022). "In addition, interaction of circulating galectin-3 with cancer cell surface MUC1 was shown to prevent anoikis." (PMID 35410995, 2022). "Therefore, as with protein antigens, the glycan chain of MUC1 can be a target for cancer immunotherapy." (PMID 36714624, 2022). "Moreover, in colorectal liver and lung metastases, a minor fraction of the cancer cells were found positive for the cell adhesion molecule Muc1 and growth factor receptor Her2/neu." (PMID 35454846, 2022). "The AR20.5-MUC1 complex can be formed with MUC1 from MUC1-positive cancer cells or in circulation." (PMID 35883508, 2022). "MUC1 is a transmembrane protein overexpressed in various tumors (such as lung, breast, pancreas, kidney, ovary, and colon tumors) aberrantly and differentially glycosylated in cancer cells as compared to normal cells." (PMID 35806376, 2022). "This may be due to the glycosylation of the oncoprotein MUC1, which undergoes abnormal changes in UC, and this abnormally glycosylated MUC1 promotes the development and progression of cancer." (PMID 35372018, 2022). "Treating MCF‐10A normal epithelial cell line expressing normal MUC1 could not induce apoptosis or inhibit cellular growth, representing selective interaction of nanobody with truncated MUC1 (tMUC1) and toxicity toward cancer cells." (PMID 34694686, 2022). "To demonstrate whether MUC1 promoted cancer cell progression via Pink1, we performed a cell viability assay and mammosphere formation assay after silencing Pink1 in both MDA-MB-468 and BT549 cell lines." (PMID 36289190, 2022). "In addition, AR2.5 internalization is achieved via dendritic cells (DCs), thus facilitating efficient MUC1 antigen processing, cross-presentation to T-cells, and the later activation of cytotoxic T-cells for eradicating cancer cells." (PMID 35883508, 2022).
cancer (continued). "In agreement with the previous studies, SZU251 + MUC1 caused a rapid induction of common cytokines such as IL6, TNFα and IFNγ in mouse BMDCs and spleen lymphocytes in vitro, favoring Th1-mediated immune responses and cytotoxic T cells acting on cancer cells." (PMID 36499455, 2022). "To further determine whether MUC1 promoted mitophagy through the Pink1-Parkin pathway, we detected Parkin expression in all three cancer cell lines, and HEK293T cells served as a positive control." (PMID 36289190, 2022). "In the following, the role of MUC1 in the growth and death of BC cancer cells is discussed." (PMID 35248049, 2022). "In dysplastic epithelium and cancers, MUC1 is detected over the entire cell surface." (PMID 36359337, 2022). "MUC1 was identified by its overexpression in breast and other human cancers." (PMID 35539431, 2022). "The MUC1 aptamer was explored as a vehicle for delivering doxorubicin to cancer cells." (PMID 36008950, 2022). "A study demonstrated that miRNA-29b and genistein loaded in MUC1 aptamer-functionalized hybrid nanoparticles (GMLHNs) could exhibit an anti-cancer effect on the NSCLC A549 cell line." (PMID 35154471, 2022). "Furthermore, humanized chimeric DMB-5F3 conjugated with ZZ-PE38 (ZZ IgG-binding protein after fusion with the Pseudomonas exotoxin) can substantially promote MUC1+ cancer cell cytotoxicity in vitro." (PMID 35883508, 2022). "MUC1 that shows abnormal expression in cancer cells might be a strong chemoattractant for immature DCs." (PMID 35883508, 2022). "In epithelial cells, disruption of the interaction between E-cadherin and β-catenin by overexpression of MUC1 may be important in the progression to carcinoma." (PMID 35568869, 2022). "Most forms of carcinomas overexpress MUC1 with various epitopes being spread over the cell surface." (PMID 35646176, 2022). "Therefore, the DOX@exosome-apt showed an enhanced tropism and effective inhibition for MUC1-positive cancer cells, providing safe and selective DOX delivery in colon adenocarcinoma." (PMID 34479611, 2021). "In summary, due to multiple functions of MUC1 in cancer progression, it is essential to realize whether MUC1 plays an initiating role in metastasis and angiogenesis." (PMID 33836774, 2021). "MUC1 has been known to prevent the activation of the intrinsic apoptotic pathway in cancer cells." (PMID 33836774, 2021). "Our results suggested that, given the unique properties of VHHs to prevent immunogenic responses andtonic signalling, our novel VHH-based anti-MUC1 CAR might be effective for clinical purposes in cancer immunotherapy." (PMID 32347044, 2021). "MUC1 is also involved in the regulation of different pathways of cancer cell growth and apoptosis." (PMID 34207342, 2021). "It has been observed that MUC1 serves different inflammatory functions in different cancers." (PMID 34207342, 2021). "Next, we analyzed whether the humanized anti-MUC1 antibodies also recognized MUC1 Tn epitopes expressed on cancer cell lines." (PMID 34070311, 2021). "Aberrant high expression of MUC1 regulates the expression of programmed death-ligand 1 (PD-L1) in cancer cells, which could prevent cancer cells from being cleared by the immune system." (PMID 34790207, 2021). "Identifying the correlation between aberrantly overexpressed MUC1 and angiogenetic-induced factors may represent a better comprehension in the development of novel therapeutic agents for cancer patients." (PMID 33836774, 2021). "In the past, researchers have designed cancer therapeutic regimens based on MUC1 characteristics to maximize its potential as a therapeutic and prognostic target, used MUC1 as an immunogen to make vaccines, and controlled the expression of MUC1 to treat undesirable cancer-related phenomena." (PMID 34207342, 2021). "fabricated a SERS-colorimetric dual-mode aptasensor for cancer biomarker MUC1 detection." (PMID 33718215, 2021). "MUC1 is an overexpressed transmembrane mucin glycoprotein in some cancer cells." (PMID 34479611, 2021).
cancer (continued). "High MUC1 expression also reduces cancer cell sensitivity to radiation in vitro and in vivo." (PMID 34681277, 2021). "The authors concluded that such action of flavonoid could be correlated with decreased proliferation and metastasis as specific, sugar cancer-related antigens, present on MUC1, were reduced." (PMID 34681197, 2021). "In addition, it has been reported that MUC1 is overexpressed in a variety of cancer tissues including in pancreatic, breast, ovarian, lung, and colon carcinomas." (PMID 34681277, 2021). "MUC1 is a transmembrane glycoprotein, overexpressed in many types of cancer, including NSCLC." (PMID 33025047, 2021). "MUC1 also plays an intrinsic role in cancer cell immune evasion through its cytoplasmic domain." (PMID 34681277, 2021). "Moreover, MUC1 is overexpressed in many cancer types, including colorectal, cervical, and breast cancer cells, and is hypoglycosylated compared to normal epithelia." (PMID 34638920, 2021). "MUC1 is a transmembrane glycoprotein whose extracellular domain contains a variable number of tandem repeats (VNTRs) regions that are highly glycosylated in normal cells and under-glycosylated in cancer." (PMID 33672244, 2021). "In addition, a series of findings have indicated that MUC1 is an attractive target for anti-cancer treatment." (PMID 34681277, 2021). "However, the inhibitory effect of monotherapy with cisPt and mAb as well as anti-MUC1 combined with PtPz4, PtPz6, and cisPt on Bcl-2 mRNA support rationality of applied therapy in anti-cancer treatment." (PMID 34206951, 2021). "Also, in hematological and pancreatic cancers, CAR T cells targeting hypoglycosylated MUC1 showed cancer regression." (PMID 33737613, 2021). "Similarly as what had been proved in our previous study and other types of cancers 16,33-37, our data showed that the expression of MUC1 protein was significantly up-regulated in ICC tissues." (PMID 34729096, 2021). "Specific fields distinguish and classify mutated epitopes (neoepitopes), tumor-associated antigens (TAA) such as differentiation or tissue-specific antigens (e.g., Melan-A, PSA), overexpressed antigens (e.g., HER-2, Muc-1), or cancer-germline antigens (e.g., MAGE, NY-ESO1)." (PMID 34504503, 2021). "Among MUC1 functions discussed here, it is rather required more investigation into the finding of which oncogenic pathway plays initiating roles in angiogenesis, and which fosters involves in invasion, proliferation, and metastasis of cancer cells in response to aberrantly overexpressed MUC1." (PMID 33836774, 2021). "Thus, underglycosylation of MUC1 on cancer cells can generate glycans truncated at the initial GalNAc (Tn), leaving them exposed for targeting." (PMID 33532593, 2021). "We confirmed that MUC1 is a potential cancer antigen for CCA." (PMID 33737613, 2021). "However, clinical trial results involving MUC1-based cancer vaccines to date have had limited success." (PMID 34065557, 2021). "MUC1 provides survival advantage to cancer cells by scavenging oxidative stress." (PMID 34681277, 2021). "Interestingly, MUC1 is also an important signaling protein in neural tracking and plays a role in perineural invasion of cancer cells which supports future investigations on the tumor—neuron interactions in t-NEPC progression." (PMID 33572108, 2021). "StcE was shown previously to cleave the entire MUC1 expressed on cancer cells, but this may be due to cleavage outside the TR region as the proposed StcE cleavage motif (S/T-X-S/T) is absent from the well-conserved TRs48,52." (PMID 34210959, 2021). "Tn and T antigens are typical carbohydrate cancer antigens present on MUC1." (PMID 34681197, 2021). "Interestingly, one recent study reveals that MUC1 can activate PD‐L1 expression in NSCLC cells for repression of immune effectors during cancer development." (PMID 33539648, 2021).
cancer (continued). "Thus, this aptamer, targeting the underglycosylated MUC1 overexpressed on the surface of cancer cells, presents a promising targeting ligand for the design of a novel delivery system aimed at TNBC." (PMID 33532593, 2021). "Mucin 1 (MUC1) was the specific TAA that was selected for CAR T cell targeting in the present study since it was reported as a second most attractive target antigen for cancer immunotherapy." (PMID 33737613, 2021). "Consistent with this, MUC1 has shown promising results in cancer vaccines." (PMID 33692796, 2021). "The DNA aptamer could bind to a wide variety of human cancer cells, and treatment of MUC1/Y positive cells resulted in reduced growth in vitro." (PMID 34452200, 2021). "Notably, compared to MUC1 expressed by healthy cells, cancer-derived MUC1 is aberrantly glycosylated, exhibiting GalNAcα1-Ser/Thr modification (Tn antigen) and other truncated O-glycans due to a lack of core 1 β3-galactosyltransferase (T-synthase) activity." (PMID 34066318, 2021). "Several cell membrane glycoproteins, such as MUC1, CD44v6, and integrins, are known to carry unsubstituted TF antigen in various cancers, such as colon, breast, and pancreatic cancer." (PMID 34944925, 2021). "The use of a MUC1 aptamer could also be used with a wide variety of cancers, as nearly all carcinomas overexpress MUC1." (PMID 33532593, 2021). "Moreover, the CA19-9 on MUC1 had the most important increase (87%) in cancer patients with 4% of the control subjects." (PMID 33672926, 2021). "There are various truncated forms of MUC1, and MUC1-C* is highly expressed in cancer." (PMID 32380650, 2020). "Much work has been done preclinically and clinically on evaluating MUC1 in anti-cancer vaccination." (PMID 32942747, 2020). "Mucin 1 (MUC1) is a transmembrane glycoprotein involved in tumorigenesis of diverse cancers." (PMID 33106534, 2020). "MUC1 overexpression and aberrant glycosylation could promote the oncogenesis and metastasis of various malignant tumors including NSCLC." (PMID 32392378, 2020). "Moreover, MUC1 carrying the ST glycan is the dominant MUC1 glycoform found in sera of cancer patients." (PMID 33149188, 2020). "Finally, the presence of MUC1-aptamer, allows for the active targeting of payload to MUC1-expressing cancer cells while avoiding undesirable accumulation in healthy cells." (PMID 32842557, 2020). "But EGFR signaling activation increased MUC1 gene expression in some cancer cell lines." (PMID 32938364, 2020). "Cancer-specific MUC1 has a functional role in the progression of PDAC." (PMID 33379259, 2020). "Previously, a MUC1-dependent activation of NF-κB was described in several cancer entities." (PMID 32486375, 2020). "Another way to eliminate cancer cells is the combination of MUC1 antibodies and radioisotopes." (PMID 32745356, 2020). "However, in cancer cells, MUC1 mostly displays hypoglycosylation of the core glycans, like sialyation of Tn and T antigens via sialyltransferase enzymes that lead to premature chain termination." (PMID 33167508, 2020). "By targeting the COX-2 and MUC1, there is a potential to improve cancer immunogenicity." (PMID 31941061, 2020). "Although MUC1 in cancer cells is not directly produced by gene mutation, but its aberrant glycosylation and conformation changes are partly due to the mutation of other genes such as loss-of-function mutations in Cosmc gene in cancer cells." (PMID 32194541, 2020). "Therefore, it is in accordance that overexpression of MUC1 in transgenic mice increased the recruitment of M2-type macrophages and created a proinflammatory environment, which promoted cancer development." (PMID 32429133, 2020). "Moreover, SERPINE1 expression in cells found in the stroma around the edges of the cancer cell nests is significantly correlated with MUC1-ST expression." (PMID 33149188, 2020).